NF1 (neurofibromin 1)
Diseases named in the same sentence as NF1 in open-access papers (continued):
Sharing a sentence is not in itself a finding about the gene and the disease.
cancer (continued). "Patients with NF1-MPNST and aberrant expression of ATRX had a significantly decreased survival rate, and the authors suggest it could be used as a prognostic marker in this cancer." (PMID 37173979, 2023). "This suggests that NF1 patients (as opposed to sporadic MPNST) would have an advantage in fighting against cancer, but this idea does not translate in the clinic, meaning that other mechanisms may counterbalance." (PMID 34445326, 2021). "Using DNA copy number copy number data from 9744 cancer specimens belonging to 39 cancer subtypes, we show that linear deletion limitation exists, and exploit it to expose deletion-limiting genes for seven deletion targets (CDKN2A, RB1, PTEN, MAP2K4, NF1, SMAD4, and LINC00290)." (PMID 31341961, 2019). "To test this hypothesis, we probed the activity of BET/MEK inhibitor combinations in cancer cell lines with and without RAS pathway mutations (mutations in RAS, BRAF, or NF1), and with varying levels of sensitivity to GSK525762." (PMID 29674704, 2018). "Although NF1 patients have a 10–15 years shorter life expectancy, the mean age at diagnosis for most tumors with high NF1 mutation frequency falls within their lifetime, ruling out the arguments that NF1 patients would not live long enough to actually develop frank cancers." (PMID 30479396, 2018). "So, germline mutations in NF1 gene leads to the formation of a truncated or non-functional neurofibromin which in turn activates or up-regulates the RAS-dependent signaling pathways, followed by the formation of benign or malignant tumors." (PMID 27980226, 2017). "Although not specific to NF1, the National Cancer Data Base is a program established by the American College of Surgeons in collaboration with the American Cancer Society to provide oncology results from Commission on Cancer (CoC)-accredited hospital registries." (PMID 28066715, 2016). "Among the ten genes, five of the TSGs (ATM, APC, BRCA2, NF1, and PTEN) were annotated with positive effects on apoptosis; the other three TSGs (PEG3, SPARC, and RPS6KA2) were also reported to increase apoptosis in sporadic epithelial OVC or other types of cancer." (PMID 22952919, 2012). "Of the 186 patients without germline P/LP variants and available cancer genomes–exomes, 41/186 patients had a somatic variant in the DNA damage response pathway (ATRX, ATM, PPM1D, POLE) and 21/186 had a variant in the MAPK-ERK pathway (BRAF, NF1, PTPN11, MAPK12)." (PMID 40072012, 2025). "We report that FA-DEX-VBL-SPION could induce cytotoxic effects on the caspase-3, PDL-1, NF-1, and H-ras gene expression levels, and lead to a reduction in cancerous cells, thereby effectively controlling cancer progression without toxicity to healthy cells compared with void VBL and FA-DEX-SPION." (PMID 33076247, 2020). "Two of the 77 patients pursued genetic testing due to cascade testing for an LPV/PV in a non-PGL/PCC gene, and because they underwent pan-cancer panel testing, were identified to have an SDHA and an NF1 LPV/PV, respectively." (PMID 39539798, 2024). "In the 235 extracranial solid tumors with histologies not included in prior pediatric pan-cancer analyses, the recurrently altered genes uniquely containing oncogenic alterations (compared to the common tumors) were CTNNB1, DICER1, and NF1." (PMID 38992034, 2024).
cancer (continued). "Our study has the limitation that we were not able to evaluate some genetic alterations reported in CNS GCTs, such as NF1, CBL, and FGD6, which are not covered by the Oncomine Pan-Cancer Cell-Free Assay." (PMID 32868820, 2020). "Up-regulation of NF1, RB1 and SUFU shows a negative effect on cancer growth, consistent with our previous report." (PMID 21765906, 2011). "However, some recurrent cancer drivers (KRAS, PI3KCA, NRAS, NF1) were reported to drive non-cancer clonal expansion only in one or two organ systems." (PMID 35078504, 2022).
genetic disorder (124 papers, 2008 to 2026). "Neurofibromatosis type 1 (NF1) and NF2-related schwannomatosis (NF2-SWN) are distinct genetic disorders caused by pathogenic variants in the nf1 and nf2 genes, respectively." (PMID 40510571, 2025). "NF1 is a complex, multisystem genetic disorder characterized by a spectrum of mutations within the NF1 gene." (PMID 41261655, 2025). "Neurofibromatosis type 1 (NF1) is a complex, multisystem, genetic disorder caused by germline NF1 variants that predispose affected individuals to tumors of the nervous system." (PMID 41294711, 2025). "Usually, this condition is associated with NF type 1 (NF-1), a common inherited genetic disorder with an autosomal-dominant inheritance form." (PMID 38957521, 2024). "NF1 is a common genetic disorder caused by defects in the NF1 gene, which encodes the protein neurofibromin." (PMID 39483902, 2024). "Among the familial cases, MEN2 was the most common genetic disorder, affecting 23% of the sample, with a further 4 cases associated with NF1, MAX, and SDHB pathological variants." (PMID 36896586, 2023). "The most well-known genetic disorder associated with familial cardiac schwannomas is neurofibromatosis type 1 (NF1), and type 2 (NF2)." (PMID 37240461, 2023). "In our cohort, we also noticed a unique MTC case (FUSCC-24) with concomitant neurofibromatosis type 1 (NF1), a multi-system genetic disorder caused by pathogenic alterations in a tumor suppressor gene NF123." (PMID 36344509, 2022). "Neurofibromin, a protein encoded by the NF1 gene, is mutated in neurofibromatosis 1, one of the most common genetic diseases." (PMID 33602260, 2021). "This is relevant also for the (hopefully soon) clinical use of mutation-targeted therapy for NF1, as well as for other genetic disorders." (PMID 33673681, 2021). "ddPCR is widely used for noninvasive prenatal detection of various types of mutations in many genetic diseases such as monogenic hereditary diabetes mellitus and mutations in the NF1 and CFTR genes." (PMID 33925253, 2021). "Neurofibromatosis type 1 (NF1), also called von Recklinghausen’s disease, is a genetic disorder caused by a mutation in or a deletion of the neurofibromin gene, which is characterized by the development of multiple tumours on nerves throughout the body." (PMID 31801570, 2019). "Neurofibromatosis 1 (NF1) is one of the most common genetic disorders and is caused by mutations in the NF1 gene." (PMID 27999334, 2016). "Neurofibromatosis type 1 (NF1), a genetic disease that affects 1 in 3,000, is caused by loss of a large evolutionary conserved protein that serves as a GTPase Activating Protein (GAP) for Ras." (PMID 24278035, 2013). "This human genetic disease, which is caused by mutations of the NF-1 tumor suppressor gene, has an incidence of about one in every 2500 live births and has a high rate of spontaneous mutations." (PMID 21569290, 2011). "However, both entities tend to occur early in life and are associated with the genetic disorder neurofibromatosis type 1 (NF-1), which is known to cause increased radiosensitivity." (PMID 35832560, 2022). "On the one hand, NF1 is a genetic disorder resulting from mutations in the NF1 gene." (PMID 34566848, 2021). "Notably, the frequency of NF1 splice variants resulting in aberrant mRNA splicing is significantly higher than that of mutated genes in other genetic diseases." (PMID 34573290, 2021). "NF-1 is a multisystem genetic disorder caused by the mutation of a gene on chromosome 17." (PMID 31932978, 2020). "In line with the main objectives of this review, the findings were grouped into three main categories based on the type of genetic disorder addressed in the selected studies: (a) NF1, (b) DS, and (c) FXS." (PMID 41346502, 2025).
genetic disorder (continued). "Hereditary predisposition was notable, with 12.2% (n = 218) of cases linked to the VHL syndrome and 5.6% (n = 100) to other genetic disorders (e.g., MEN2, NF1)." (PMID 41283059, 2025). "The findings of this study are particularly relevant to the minority population diagnosed with NF1, shedding light on the unique challenges they face and advancing research in the field of genetic disorders." (PMID 40481533, 2025). "While certain issues faced by patients with conditions like NF1 are disease-specific, many challenges are common shared across rare genetic diseases." (PMID 40608210, 2025). "This resource can be mined to identify candidate therapeutic targets for genetic diseases, including NF1." (PMID 41294711, 2025). "The studies analyzed several genetic disorders, primarily NF1, examined in 77.8% of the studies, DS (11.1%) and FXS (11.1%)." (PMID 41346502, 2025). "NF1 is a common genetic disease that is estimated to affect 1 in 3100 people worldwide that occurs when one copy of the NF1 gene has a loss‐of‐function mutation, leaving patients with only one functioning allele of NF1." (PMID 40812791, 2025). "Ultimately, the integration of AI into NF1 diagnostics holds great promise for enhancing the quality of life and long-term prognosis of individuals living with this complex genetic disorder." (PMID 40428382, 2025). "NF-1 is a rare genetic disease that affects multiple systems, including the skin, bones, joints, respiratory system, and nervous system." (PMID 38816890, 2024). "NF-1 is one of the most common hereditary diseases with an estimated prevalence of 1 in 2,500 to 1 in 3,000 persons worldwide." (PMID 34988040, 2021). "Announcing the diagnosis of a genetic disorder such as NF1 is a critical event in the lives of both the child and the parents." (PMID 32014052, 2020). "Neurofibromatosis type 1 (NF1) is a common genetic disorder of deregulated cell growth, occurring in about 1 in 3,000 individuals, caused by germline mutations in the neurofibromin-encoding gene NF1." (PMID 32352002, 2020). "Neurofibromatosis 1 (NF1) is one of the most common dominantly inherited genetic disorders with a worldwide incidence of at least one in 3000 individuals." (PMID 31717729, 2019). "Neurofibromatosis 1 (NF1) is one of the most common genetic diseases in humans, with a prevalence of one case in 3,000 births." (PMID 25885768, 2015). "Additional case reports or case series would give us a better understanding of the relationship between occipital neuralgia and NF-1 as well as the efficacy of OPNS in the treatment of occipital neuralgia in patients with this genetic disorder." (PMID 21569290, 2011). "Further research is needed to clarify the mechanisms underlying splicing disruption by synonymous variants, which may ultimately contribute to improved diagnosis and targeted therapies for NF1 and other similar genetic disorders." (PMID 40417234, 2025). "Neurofibromatosis 1 (NF1) is a genetic disorder present in approximately 1/3,000 live births." (PMID 38258905, 2024). "NF-1 is a rare genetic disorder occurring in 1 per 3000 live births, with an autosomal dominant inheritance trait in 50% of the cases, and arises due to mutation of NF-1 tumour suppressor gene located on 17q22.1 chromosome which encodes a protein neurofibromin." (PMID 37274990, 2023). "Neurofibromatosis 1 (NF1) is a common genetic disorder that affects about 1 in 3500 people." (PMID 32204567, 2020). "TSC and NF1 are the most common genetic disorders with cutaneous and neurological involvement." (PMID 32894194, 2020). "Neurofibromatosis 1 (NF1) is a common genetic disease, affecting approximately 1 in 3,500 subjects." (PMID 32694667, 2020). "The prevalence of DD found in the NF1 sample is much higher than that, but, together with the presence of the genetic disorder, this could be related to the use of highly specific and sensitive neurocognitive diagnostic techniques." (PMID 24936179, 2014).
genetic disorder (continued). "In previous studies, the combination of pravastatin and zoledronate, known as the ZOPRA treatment, was shown to accelerate the RIANS and to decrease radiosensitivity in a number of genetic diseases, including HD, TSC, NF1, and XPD." (PMID 35163494, 2022). "Neurofibromatosis 1 (NF1, OMIM 162200) is one of the most common genetic disorders, and presents full penetrance and variable phenotypic expression." (PMID 29476678, 2018). "The frequency of PNETs with hereditary disease is high in the order of MEN1, VHL, NF-1 and TSC." (PMID 22824559, 2012).
benign tumors (37 papers, 2006 to 2026). "Tumors with loss of NF1, both benign tumors such as pNF, and high-grade malignancies including MPNST, are characterized by hyperactivation of RAS/RAF/MEK/ERK signaling." (PMID 41023593, 2025). "While the optimal PET/CT threshold for distinguishing MPNSTs from benign tumors associated with NF1 is still debated, some studies suggest that 18F-FDG PET/CT provides sufficient accuracy for detecting MPNSTs." (PMID 40182390, 2025). "This study provides insight into the progression of benign tumors and novel therapeutic approaches for treatment of NF1-associated MPNSTs." (PMID 34948100, 2021). "The success of selumetinib and other MEK inhibitors for NF1-associated PNs and other benign tumors represents a major milestone in therapy for this disease." (PMID 32353955, 2020). "Our results may provide a basis for the progression of benign tumors and novel therapeutic strategies for NF1-associated MPNSTs." (PMID 34948100, 2021). "The NF1−/− plexiform neurofibroma derived Schwann cells provide a useful cell culture model of these benign tumors, and provide a logical platform for studying progression to MPNST." (PMID 32353955, 2020). "More importantly, most of the NF1 patients only have benign tumors with relatively long overall survival, which indicates that regular clinical follow-ups are required for these individuals." (PMID 32850344, 2020). "In summary, we present consistent evidence in both human and mouse models that the NF1+/− microenvironment has an antagonistic role in tumorigenesis: accelerating development of benign tumors and restraining further progression to malignant cancer." (PMID 30479396, 2018). "In brief, we discover that an Nf1+/− microenvironment accelerates the formation of benign tumors but impairs further progression to malignancy." (PMID 30479396, 2018). "In our previous study, based on reverse transcription–polymerase chain reaction (RT-PCR)-based differential display analysis, we found that interferon-induced transmembrane protein 1 (IFITM1) was downregulated in MPNST tissues of patients with NF1 compared to that in benign tumor tissues." (PMID 39273214, 2024). "It was also shown that benign tumours and peripheral nerves share the same spliced RNA expression profile, indicating that in benign tumours, NF1 may be spliced identically." (PMID 35008787, 2021). "In a methylation analysis of MPNSTs, although no significant methylation changes in the NF1 gene promoter were found in the MPNST tissues, frequent PTEN promoter methylation was detected in NF1-associated MPNST tissues and NF1-deficient MPNST cell lines, although not in benign tumors." (PMID 25109740, 2014). "Notably, younger age, malignant transformation of a former benign tumor and the presence of NF1 did not significantly influence outcome (p > 0.05)." (PMID 21106096, 2010). "However, NF1 locus LOH in Schwann cells is frequently observed in benign plexiform neurofibromas, suggesting that additional modifier factors may be involved in the malignant transformation of benign tumors to MPNST." (PMID 39273214, 2024).